TIGIT (T cell immunoreceptor with Ig and ITIM domains)
Diseases named in the same sentence as TIGIT in open-access papers (continued):
Sharing a sentence is not in itself a finding about the gene and the disease.
bladder cancer (continued). "Thus, our study provided novel insights into immunosuppression in bladder cancer and highlighted TIGIT as a novel target for immunotherapy of bladder cancer." (PMID 35069212, 2021). "Thus, we aimed to establish a bladder cancer orthotropic model and then compare the antitumor capacity of α-PD-1 and α-TIGIT." (PMID 35069212, 2021). "As expected, TIGIT was highly expressed on the surface of Treg cells from bladder cancer tissues." (PMID 35069212, 2021). "Thus, our data indicated that targeting TIGIT inhibited the metastasis of bladder cancer cells by suppressing the expression of IL-32." (PMID 35069212, 2021). "Because IL-32 mediates the metastasis and invasion of bladder cancer cells, targeting TIGIT might inhibit the metastasis of bladder cancer by suppressing the expression of IL-32." (PMID 35069212, 2021). "We found that IL-32 was colocalized with FOXP3 and TIGIT in clinical bladder cancer samples." (PMID 35069212, 2021). "Nevertheless, targeting TIGIT not only reversed immunosuppression by restoring the antitumor immune response mediated by T cells but also suppressed the secretion of IL-32 and inhibited the metastasis of bladder cancer cells." (PMID 35069212, 2021). "In addition, targeting TIGIT with anti-TIGIT monoclonal antibodies suppressed the metastasis of bladder cancer and reversed its antitumor activities." (PMID 35069212, 2021). "Our results clearly demonstrated that targeting TIGIT suppressed bladder cancer." (PMID 35069212, 2021). "Thus, TIGIT+ Treg cells were unambiguously enriched in bladder cancer tissues." (PMID 35069212, 2021). "Furthermore, we examined the expression of TIGIT in Treg cells from murine bladder cancer tissues." (PMID 35069212, 2021). "Importantly, targeting TIGIT with anti-TIGIT antibodies not only enhanced the antitumor activities of T cells but also suppressed the abundance of IL-32, in turn inhibiting the metastasis of bladder cancer cells." (PMID 35069212, 2021). "We developed a five-gene signature (including VAMP5, TIGIT, LCK, CD27 and CACYBP) based on tumor-specific T cell-related genes to predict the immunotherapy response in bladder cancer patients." (PMID 39033098, 2024). "In conclusion, we have developed and validated a novel tumor-specific T cell signature (including VAMP5, TIGIT, LCK, CD27, and CACYBP) as a prognostic biomarker for bladder cancer patients treated with immunotherapy using single cell multi-omics data." (PMID 39033098, 2024). "To explore the regulation of α-TIGIT in Treg cells, we analyzed the expression of CD25, TIGIT, and FOXP3 in murine bladder cancer tissues." (PMID 35069212, 2021). "This study provides a comprehensive analysis of the intricate immune profiles of three relevant co-receptors—TIM-3, LAG-3, and TIGIT—in the most relevant non-urothelial subtypes of bladder cancer." (PMID 40647508, 2025). "Since the expression of TIGIT and PDCD1 on the CD8 T cells are widely used to identify dysfunction or early activated effector T cells in several cancer types such as bladder cancer, these markers alone are insufficient to define terminally exhausted CD8+ T cell in CRC." (PMID 40799645, 2025). "Therefore, our study aimed to investigate the role of tumor-specific T cells in bladder cancer immunotherapy by constructing TstcSig, consisting of five tumor-specific T cell-related genes: CD27, CACYBP, TIGIT, LCK, and VAMP5." (PMID 39033098, 2024). "Furthermore, Kaplan-Meier survival analysis revealed that the higher expression of VAMP5, TIGIT, LCK, CHORDC1, CD27, and CACYBP was correlated with better outcomes in bladder cancer patients treated with immunotherapy." (PMID 39033098, 2024). "Moreover, TIGIT blockade can improve the efficacy of anti-PD-1 therapy and promote the stimulation of tumor-infiltrating CD8+ T-cells in patients with bladder cancer." (PMID 34638729, 2021).
bladder cancer (continued). "This study elucidates the immunogenic landscape of these rare bladder cancer subtypes, laying the groundwork for future trials using antibodies that are currently in clinical development to expand therapeutic options by including TIM-3, TIGIT, and LAG-3 into the immunomodulatory armamentarium." (PMID 40647508, 2025). "In addition, we detected higher frequencies of TIGIT+ Treg cells only in bladder cancer tissues but not in spleen tissues or peripheral blood cells." (PMID 35069212, 2021). "Interestingly, TIGIT molecules have been identified on the surface of CD8+ T cells in bladder cancer, but their function has not been well characterized." (PMID 35069212, 2021). "An in-depth characterization of TILs in bladder cancer using PBMC isolation and tumor single-cell isolation from fresh tumor tissue demonstrates that PD-1highTOX+ T cells play a key role in tumor evasion, which might be reversed by combining PD-1 and TIGIT inhibition." (PMID 35656508, 2022).
metastatic melanoma (12 papers, 2016 to 2024). A melanoma that has spread from its primary site to another anatomic site. "Combining anti-TIGIT and anti-PD-1 immunotherapy in metastatic melanoma has shown encouraging outcomes, with increased proliferation, cytokine generation, and degranulation of effector CD8+ T cells." (PMID 35656508, 2022). "Dual PD-1/TIGIT blockade and dual PD-1/Tim-3 blockade are both potential strategies that are being assessed in metastatic melanoma." (PMID 29996914, 2018). "The blockade of additional immune checkpoints, especially TIGIT and LAG-3, has been extensively explored, but so far only a LAG-3 antibody has been approved for combination with nivolumab to treat unresectable or metastatic melanoma." (PMID 37332070, 2023). "A more recent study reported that anti-TIGIT mAbs enhanced IL-15-driven NK cell cytotoxicity in both B16F10 and LWT1 metastatic melanoma-bearing mice." (PMID 33670993, 2021). "In patients with metastatic melanoma, CD8+ TILs upregulate TIGIT and downregulate CD226, leading to an imbalance of TIGIT/CD226 expression." (PMID 31379886, 2019). "CD8+ TILs exhibited downregulation of the costimulatory molecule CD226, which competes with TIGIT for the same ligand, supporting a TIGIT/CD226 imbalance in metastatic melanoma." (PMID 29996914, 2018).
multiple sclerosis (12 papers, 2018 to 2025). A progressive autoimmune disorder affecting the central nervous system resulting in demyelination. "TIGIT has been shown to be differentially increased in GBM TILs compared to those in multiple sclerosis." (PMID 39346924, 2024). "Lucca and colleagues also found that PD-1/PD-L1 expression levels were comparable between GBM and multiple sclerosis, suggesting that TIGIT is likely exerting its own unique inhibitory effect in the TME regardless of heavy co-expression with other ICs." (PMID 39346924, 2024). "Tregs expressing TIGIT supressed Th1 and Th17 cell responses and signalling through TIGIT on functionally defective Tregs from patients with multiple sclerosis restored suppressive function, highlighting the potential of TIGIT-targeting." (PMID 38077329, 2023). "Interpretation: This is an initial exploration of the utility of CTLA-4, PD-1, TIM-3, LAG-3, and TIGIT expression levels as prognostic indicators in untreated, recently diagnosed multiple sclerosis." (PMID 31134049, 2019). "Therefore, the expression of TIGIT along with Tim1 defines a bona fide regulatory B cell subset whose function is dysregulated in patients with multiple sclerosis." (PMID 41177809, 2025). "Interestingly, a recent study demonstrated that TIGIT signaling enhances the function of FOXP3+ Tregs from patients with multiple sclerosis by upregulating Foxo1 that blocks T-bet expression and limits IFN-γ secretion." (PMID 34314385, 2021). "However, excessive TIGIT inhibition may lead to multiple sclerosis, underscoring the need to determine the optimal dosing for TIGIT inhibition as a critical research direction." (PMID 40994140, 2025). "Previous studies report that TIGIT+ Tregs selectively suppress Th1 and Th17 responses and TIGIT signaling counteracts IFN-γ production in Th1 Treg cells which are dysregulated in multiple sclerosis." (PMID 35911690, 2022).
psoriasis (12 papers, 2021 to 2025). An autoimmune condition characterized by red, well-delineated plaques with silvery scales that are usually on the extensor surfaces and scalp. "In recent years, studies have found that patients with psoriasis lack or downregulate TIGIT+ T cells, and the expression of TIGIT is negatively correlated with the severity of psoriasis." (PMID 38791423, 2024). "A study utilized spatial transcriptomics to compare the expression of inhibitory T cell ICs, specifically CTLA-4, TIGIT, LAG-3, and PDCD1 (encoding PD-1), on tissue-resident memory T cells in patients with dermatomyositis (Th1-driven) and psoriasis (Th17-driven)." (PMID 38817600, 2024). "In humans, TIGIT expression is correlated with psoriasis severity." (PMID 36944702, 2023). "Moreover, we observed higher CTLA-4 and TIGIT expression by Foxp3int Tregs of PsA patients as compared to psoriasis patients (CTLA-4 + Tregs: 2.3% vs. 3.3%, P= 0.040)(TIGIT + Tregs: 63.2% vs. 69.1%, P = 0.017)." (PMID 36450783, 2022). "While CD28, TIGIT, BTLA and PD-1 are expressed by CD8 T cells, the costimulatory receptors LIGHT and CD134 are minimally expressed in both psoriasis patients and healthy controls (<2%)." (PMID 40391222, 2025). "TIGIT plays a role in inhibiting CD4 + T cell responses and has been reported to be downregulated in psoriasis." (PMID 39684538, 2024). "TIGIT expression levels on CD4+ T cells of psoriasis vulgaris (PV) patients are significantly reduced and it is negatively correlated with psoriasis area and severity index." (PMID 35720417, 2022).
systemic lupus erythematosus (12 papers, 2015 to 2025). An autoimmune multi-organ disease typically associated with vasculopathy and autoantibody production. "In lupus mice, the TIGIT-immunoglobulin fusion protein can attenuate the immune response and inhibit the production of some autoantibodies." (PMID 37978415, 2023). "In IMQ-induced lupus model, the proportion of hu-TIGIT-expressing cells in KI mice was comparable to that of mo-TIGIT-expressing cells in WT mice, and mo-TIGIT-expressing cells in KI mice were not increased." (PMID 37161050, 2023). "Tfr cells which express high level of TIGIT repress the production of anti-dsDNA IgA in pristane-induced lupus mouse model." (PMID 35720417, 2022). "It has been shown that TIGIT-Ig postponed onset of proteinuria and reduced serum concentrations of autoantibodies in murine lupus." (PMID 35844584, 2022). "In lupus-prone (NZB/NZW F1) mice model that was treated with TIGIT-Ig fusion protein, the onset of SLE was delayed, proteinuria and autoantibodies production were reduced, inflammatory response was inhibited and survival was prolonged compared to those of the controls." (PMID 35720417, 2022). "However, we did not study other known markers for Tregs such as CD127 and Helios which have already been evaluated in lupus or new markers such as TIGIT or FCRL3." (PMID 26629828, 2015). "In addition, TIGIT signaling suppressed CD4+ T-cell responses in systemic lupus erythematosus." (PMID 35844584, 2022). "Due to elevated expression levels in T cells, TIGIT may serve as a clinical biomarker in systemic lupus erythematosus (SLE) and rheumatoid arthritis." (PMID 40574024, 2025). "Previous studies also showed that TIGIT-expressing T cells possessed a functionally proinflammatory profile and memory phenotype in context of experimental acute kidney injury, donor-specific hyperresponsiveness (DSH) and systemic lupus erythematosus (SLE)." (PMID 38545097, 2024). "To assess the effects of elevated IFN-α on regulatory T cells (Tregs) in systemic lupus erythematosus (SLE) patients, we investigated the differentiation of Th1-like Tregs under in-sequence and out-of-sequence conditions and the reversal effect of activating TIGIT on immune suppression." (PMID 37978415, 2023).
colitis (11 papers, 2015 to 2025). Inflammation of the colon. "TIGIT deficiency protected micefrom induction of experimental colitis by reducing IL-17Aproducing CD69+CD103-CD4+ TRM cells." (PMID 40529369, 2025). "TIGIT deficiency protects mice from DSS-induced colitis by reducing IL-17A–producing CD69+CD103− CD4+ TRM cells." (PMID 35844584, 2022). "CD69+CD103− CD4+ TRM cells were the major source of interleukin-17A (IL-17A) production in the colon and TIGIT deficiency protected mice from induction of experimental colitis by reducing IL-17A–producing CD69+CD103− CD4+ TRM cells." (PMID 35844584, 2022). "Nevertheless, further studies are needed to investigate the roles of TIGIT in the pathogenesis of DSS-induced colitis and the underlying mechanisms." (PMID 35844584, 2022). "Together, this study provides new insights into the regulation of gut inflammation that TIGIT deficiency protects mice from DSS-induced colitis, which might have a potential therapeutic value in the treatment of IBDs." (PMID 35844584, 2022). "Together, we provide evidence that TIGIT might serve as a pathogenic factor in DSS-induced colitis." (PMID 35844584, 2022). "Collectively, these results suggest that CUR ameliorates experimental colitis by targeting the TIGIT/NRP1 axis, modulating gene and protein expression, and promoting an anti-inflammatory cytokine environment." (PMID 41465029, 2025). "This indicated that the TIGIT/CD155 signaling was activated abnormally in the colonic tissues of the colitis mice." (PMID 38202824, 2024). "In the present study, a significant decrease in TIGIT levels on mTreg cells and a significant increase in TIGIT levels on mTh17 cells were found in the colitis mice." (PMID 38202824, 2024). "IL-17A expression in CD69+CD103− CD4+ TRM cells was impaired in TIGIT−/− mice during the induction of colitis." (PMID 35844584, 2022). "Here, we showed that TIGIT was required for IL-17A production by CD69+CD103− CD4+ TRM cells during DSS-induced colitis." (PMID 35844584, 2022). "Our further data revealed that TIGIT expression was notably increased in CD4+ T cells from DSS-induced colitis." (PMID 35844584, 2022). "TIGIT deficiency led to decreased numbers of CD69+CD103− and CD69+CD103+ CD4+ TRM cells in the colon during DSS-induced colitis." (PMID 35844584, 2022). "We next analyzed TIGIT expression among subsets of CD4+ T cells from DSS-induced colitis by flow cytometry." (PMID 35844584, 2022). "Here, our data revealed TIGIT expression in CD4+ T cells from LPMC was notably increased in mice with DSS-induced colitis." (PMID 35844584, 2022). "Here, our data revealed that TIGIT−/− mice were resistant to DSS-induced colitis when compared with WT mice." (PMID 35844584, 2022). "TIGIT deficiency impairs IL-17A production in CD69+CD103− CD4+ TRM cells specifically, resulting in lower disease activity index and reduced pathological injury in mice with DSS-induced colitis." (PMID 35844584, 2022). "We further investigated the role of TIGIT in T-cell residency during DSS-induced colitis." (PMID 35844584, 2022). "TIGIT expression is strongly increased in colonic CD4+ T cells from mice with DSS-induced colitis." (PMID 35844584, 2022). "TIGIT expression was increased in CD4+ T cells in the gut of mice with DSS-induced colitis." (PMID 35844584, 2022). "TIGIT expression was similar in CD4+ T cells from the spleen of colitis or control mice." (PMID 35844584, 2022). "Importantly, APS reversed the expression changes in the TIGIT molecule on mTh17/mTreg cells in the colitis mice with fewer CD4+CCR6+TIGIT+, CD4+CCR7−CCR6+TIGIT+ and CD4+CCR7−CCR6+TIGIT+ cells and more CD4+Foxp3+TIGIT+, CD4+CCR7−Foxp3+TIGIT+ and CD4+CCR7−Foxp3+TIGIT+ cells." (PMID 38202824, 2024). "In future research, we plan to utilize both global and conditional knockout models of the TIGIT/NRP1 genes in mice, including specific T cell populations, to induce colitis and develop cellular models of UC." (PMID 41465029, 2025).
colitis (continued). "Although CD69+CD103+ cells accounted for the majority of Treg cells in both colons, TIGIT expression in Treg cells was not different in mice with or without colitis." (PMID 35844584, 2022). "Flow cytometry analysis revealed that most of the CD4+ and CD8+ T cells from the colons of TIGIT−/− or WT mice without colitis did not express CD62L." (PMID 35844584, 2022). "In this study, we found that treatment with rTsPmy significantly increased the expression of TIGIT within CD4+Foxp3+ T cells and the proportion of CTLA4+Foxp3+ Treg cells in CD4+ T cells in mice with colitis compared with mice with colitis that received PBS only." (PMID 34336843, 2021). "Notably, TIGIT/NRP1 knockout or knock-in mouse models were not employed to induce DSS-induced colitis, and the bioavailability of CUR in colonic mucosa and lymphoid tissues was not assessed." (PMID 41465029, 2025). "In contrast to its immunosuppressive function, research using murine models of colitis has revealed that the absence of TIGIT may alleviate intestinal inflammation and tissue damage." (PMID 41465029, 2025). "However, the absence of TIGIT protected mouse from Dextran Sodium Sulfate (DSS)-induced colitis through the regulating IL17A-producing tissue-resident memory T cells." (PMID 38545097, 2024). "Albeit it has been shown that TIGIT had T-cell–intrinsic inhibitory functions, the decreased expression of CD155 in the colon of TIGIT−/− mice could lead to reduced TIGIT/CD155 interaction, which might contribute to decreased IL-17A production during DSS-induced colitis in the current study." (PMID 35844584, 2022). "Furthermore, the suppression of Th1 and Th17 but not Th2 responses by TIGIT+ Treg was dependent on FGL2.21In vivo, FGL2 was critical in the control of effector T cell expansion by TIGIT+ Treg in lymphopenic hosts and in controlling a number of inflammatory diseases including colitis." (PMID 26241231, 2015).
renal cell carcinoma (10 papers, 2021 to 2025). "It has been reported that high expression profiling of the inhibitory receptors LAG-3, TIM-3, and TIGIT in renal cell carcinoma refers to malignancy and decreased survival." (PMID 36829161, 2023). "A similar phenotype is observed in CD8+TILs from patients with renal cell carcinoma (RCC), colorectal cancer (CRC), and NSCLC that display upregulation of PD-1, TIGIT, Lag-3, and Tim-3 with reduced CD226 expression." (PMID 33670993, 2021).
colon adenocarcinoma (8 papers, 2018 to 2026). "CYT-high tumors exhibited elevated TIGIT expression in both colon adenocarcinoma (COAD) and rectal adenocarcinoma (READ) datasets." (PMID 41596586, 2026). "Given the potential interaction between TIGIT and PD-1, we then assessed the antitumor effects of combined inhibition of TIGIT and PD-1 signals using a xenograft B6J mouse tumor model derived from MC38 colon adenocarcinoma cells." (PMID 34659197, 2021).